TET2 (tet methylcytosine dioxygenase 2)
Diseases named in the same sentence as TET2 in open-access papers (continued):
Sharing a sentence is not in itself a finding about the gene and the disease.
hematological malignancies (continued). "Heterozygous mutations in FLT3ITD, TET2, and DNMT3A are associated with hematologic malignancies in humans." (PMID 36073548, 2022). "Tet methylcytosine dioxygenase-2 (TET2) is a key enzyme of DNA demethylation that plays an important role in cardiovascular disease and hematological disease and is related to clonal hematopoiesis, inflammation and adverse vascular remodeling." (PMID 36038916, 2022). "Subsequently, a series of studies focusing on the functions of Tet2 in hematologic malignancies were conducted." (PMID 34222235, 2021). "TET2 and/or DNMT3A was mutated in human solid tumors as well as in hematological malignancies to a greater degree." (PMID 34039392, 2021). "The inactivation of the TET2 gene in both mice and humans has shown a high degree of deregulation of the hematopoiesis process leading to hematological malignancies." (PMID 34660059, 2021). "Perhaps more importantly, disruption of TET2 expression enhances the therapeutic efficacy of adoptively-transferred CD19-targeted CAR-T cells in the setting of hematologic malignancies." (PMID 34930302, 2021). "Function, expression, previous evidence of involvement in hematological malignancies and variant VAF indicated TET2 as the most notable mutated gene." (PMID 32321919, 2020). "Clonal hematopoiesis, which is a strong risk factor for subsequent hematological malignancies, was reported to be frequently associated with somatic mutations of DNMT3A and TET2." (PMID 31527484, 2019). "TET2 haploinsufficiency is enough to alter cellular properties and contribute to hematological malignancies, possibly due to a decrease in its catalytic activity." (PMID 30917865, 2019). "Future studies to further investigate the mechanisms that lead to reduced TET2 expression in hematological malignancies will be of importance." (PMID 26984174, 2016). "Both AF9 and TET2 are MLL fusion partners that regulate HOX gene transcription in hematological malignancies." (PMID 27462416, 2015). "Decreased TET2 expression was reported in patients with hematologic malignancy, which was consistent with our result." (PMID 23691452, 2012). "Given the critical role of TET proteins in regulating hematopoietic differentiation and prevention of hematological malignancies, we hypothesized that PROSER1 deficiency may mimic the effects of TET2 mutations in hematopoiesis." (PMID 40554416, 2025). "Patient outcome related to low TET2 expression in hematological disorders." (PMID 40116537, 2025). "Studies on mice and cell lines show that the function of TET2 is boosted by vitamin C. Thus, by strengthening the demethylation activity of TET2, vitamin C could play a role in the prevention of hematological malignancies in individuals with TET2 dysfunction." (PMID 36639817, 2023). "Recent studies linking vitamin C, TET2 and hematological malignancies suggest that sufficient intake of vitamin C could play a role in the prevention of these diseases." (PMID 36639817, 2023). "Detection of these highly clonal, co-occurring CH events, especially at TET2, DNMT3A, and JAK2, could be helpful in identifying individuals at increased risk of developing hematologic malignancies." (PMID 37684235, 2023). "The downregulation of TET-2 was observed in hematologic malignancies." (PMID 35965615, 2022). "Previous studies revealed that loss-of-function mutations of TET2 are frequently found in hematological malignancies, while the mutations of TET1 are not." (PMID 33705482, 2021). "Analogous to the use of DNA demethylating agents, therapeutic interventions that enhance TET2 enzymatic activity, decrease 2-HG inhibition, or restore TET2 transcription may be clinically beneficial in hematological malignancies." (PMID 34413196, 2021). "Dysregulation of TET2 can lead to both hematological malignancies as well as autoimmune conditions." (PMID 34145262, 2021).
hematological malignancies (continued). "In addition to loss-of-function mutations, aberrant transcriptional repression and proteolytic activity also impair TET2 function in hematologic malignancies." (PMID 32726753, 2020). "While the work here is focused on ESCs, these findings may have relevance for the role of DNMT3A and TET2 in hematologic malignancies." (PMID 30001199, 2018). "TET2 inactivation is the most common alteration in hematological malignancies." (PMID 28407691, 2017). "For this reason, growing attention has been given to the hypothesis that TET2 is a gate keeper in hematological malignancies." (PMID 26984174, 2016). "Notably, in an assay to quantify 5hmC in the genome of patients with various hematologic malignancies, levels of 5hmC in a significant proportion of patients with wild-type (WT) TET2 (and also WT TET1 and TET3) were as low as those from patients with TET2 mutations." (PMID 36675240, 2023). "Therefore, enhancing TET2 enzymatic activity or restoring TET2 transcription may be clinically beneficial in hematological malignancies." (PMID 36671446, 2022). "Somatic mutations in tet methylcytosine dioxygenase 2 (TET2) are another example that may result in increased self-renewal as they were described in clonal hematopoiesis without hematological malignancies." (PMID 24763223, 2014). "Ten-Eleven Translocation-2 (TET2), a member of the TET family of enzymes, has key roles in epigenetic regulation and the occurrence of hematopoietic diseases." (PMID 34732266, 2021). "Acquisition of TET2 mutations is an early clonal event in MPN with mutations in Janus kinase 2 (JAK2) and myeloproliferative leukemia oncogene (MPL), implying that loss of 5-hmC levels may have a functional role in the onset and/or progression of hematological malignancies." (PMID 24202321, 2013). "Unlike those in TET2, mutations in TET1 and TET3 are rarely observed in hematological malignancies; however, these two genes are involved in the development of hematological cancers through expression regulation." (PMID 40599235, 2025). "Indeed, the reduction of TET2 and TET3 expression is responsible for hematologic disorders/malignancies and for increasing cytokine production." (PMID 35581740, 2022). "The gene-trapped Tet2 knockout mouse developed myeloid malignancies that were transplantable to secondary recipients, while the conditional knockout mouse did not die from hematological disease." (PMID 24202321, 2013). "However, with the deletion of Tet2 in differentiated myeloid cells (using LysM-Cre), no malignancies were observed, indicating that the TET2 LOF needs to occur in early HSPCs to initiate hematologic diseases." (PMID 36675240, 2023).
cardiovascular disease (43 papers, 2018 to 2026). "With TET2 being very common as a CH-associated mutation in cardiovascular diseases, canakinumab likely plays a positive role in preventing cancers and confers the clinical benefits in disease management." (PMID 39682303, 2024). "Loss of function of Tet2 has been linked to an inflammatory phenotype in macrophages that contributes to cardiovascular disease." (PMID 38828722, 2024). "In experimental models of cardiovascular disease, studies indicate that Tet2-deficient macrophages promote disease via enhanced production of IL-1β through the NLRP3 inflammasome." (PMID 39742155, 2024). "There is some evidence in the literature supporting a link between TET2 mutations and cardiovascular disease." (PMID 36414855, 2023). "Recently, cardiovascular disease has been associated with clonal hematopoiesis, especially TET2 mutations." (PMID 37190195, 2023). "The expansion of cells with TET2 mutations within the blood is associated with increased risk for all-cause mortality, development of leukemia and cardiovascular disease." (PMID 38062031, 2023). "CHIP, and particularly TET2-mutant CHIP, is also a novel, significant risk factor for cardiovascular diseases, related in part to hyper-inflammatory, progeny macrophages carrying TET2 mutations." (PMID 31963585, 2020). "TET2 mutations are abundant in hematopoietic malignancies, and cardiovascular diseases, as well as in increased inflammatory macrophage activation in TET2 knockouts." (PMID 32849788, 2020). "Tet2 loss of function is an important driver of clonal hematopoiesis and studies in mice have demonstrated that Tet2-deficient macrophages accelerated cardiovascular disease." (PMID 32849512, 2020). "Clonal hematopoiesis driven by somatic heterozygous TET2 loss is linked to malignant degeneration via consequent aberrant DNA methylation, and possibly to cardiovascular disease via increased cytokine and chemokine expression as reported in mice." (PMID 30890702, 2019). "Somatic heterozygous TET2 loss drives clonal hematopoiesis, which is linked to malignant cell degeneration and potentially cardiovascular disease." (PMID 30890702, 2019). "Pathologically, TET2 exhibits a close association with a spectrum of cardiovascular diseases." (PMID 40067382, 2025). "Mechanistically, DNMT3A/TET2 CHIP‐driver mutations may exert their detrimental effects on cardiovascular disease predominantly by a pro‐inflammatory activation of circulating blood cells." (PMID 40702883, 2025). "CH is associated with an increased risk of cardiovascular diseases, and CH driven by mutations in one of the most prevalent driver genes, Tet methylcytosine dioxygenase 2 (TET2), is associated with a proinflammatory gene signature in circulating immune cells in both mice and humans." (PMID 41252200, 2025). "It has been suggested that cardiovascular disease and associated inflammation may drive clonal expansion of Tet2-mutant hematopoietic cells." (PMID 39742155, 2024). "Specifically, TET2 has been found to promote embryonic heart development via regulation of gene expression and chromatin region opening, whereas impaired TET2 function during embryogenesis is associated with fetal death and cardiovascular disease." (PMID 38491513, 2024). "Secondly, it would allow researchers to adjust for TET2 mutations in epigenome-wide association studies, where they are a potential confounder of associations between DNA methylation and other phenotypes such as cardiovascular disease and age." (PMID 34663818, 2021). "Interestingly, Segura-Diaz performed a targeted case-control study of 55 age-matched patients with PV and provided evidence for mutations in TET2 and higher risk of cardiovascular disease and thrombotic events." (PMID 32781570, 2020). "Moreover, deciphering the mechanisms by which TET2 loss and clonal hematopoiesis result in increased inflammation and age-related cardiovascular diseases can pave the way for therapeutic intervention." (PMID 33520997, 2020).
cardiovascular disease (continued). "In addition to being a pre-malignant state, TET2 mutated clones are associated with an increased risk of death from cardiovascular disease, which could involve cytokine/chemokine overproduction by monocytic cells." (PMID 35115654, 2022). "In addition, deficiency in TET2 provokes an inflamed immune phenotype (largely via aberrant cytokine secretion) and associates with several inflammation-based diseases, with a notable causal role in cardiovascular disease." (PMID 31963585, 2020). "Previous evidence has suggested a close correlation between TET2 and cardiovascular disease, as well as its significance for the normal differentiation of VSMCs." (PMID 40067382, 2025). "Clinical studies in patients with cardiovascular disease have identified DNMT3A, TET2, and ASXL1 genes as the most commonly mutated CHIP-driver genes, accounting for ~80% of all CHIP cases." (PMID 40278194, 2025). "In patients with TET2 and DNMT3A clonal hematopoiesis, an inflammasome hyperactivation in myeloid cells was noticed, which represents the potential cause of cardiovascular disease." (PMID 37915324, 2023). "Studies on TET enzymes have described that TET2 is involved in several types of cardiovascular diseases." (PMID 36658614, 2023). "Meanwhile, patients with CHIP, represented by JAK2V617F mutation, had a 12.1-fold increase in cardiovascular diseases (CADs), while CHIP sustained by DNMT3A, TET2, or ASXL1 had a 1.7–2-fold increase in CADs." (PMID 37915324, 2023). "Some studies have suggested that cardiovascular disease and inflammation may promote expansion of Tet2-mutant leukocytes in the peripheral blood." (PMID 39742155, 2024). "These researches showed that TET2 contributes significantly to cardiovascular disease." (PMID 36658614, 2023). "The increased mortality associated with carrying DNMT3A- and/or TET2-CHIP-driver mutations is independent of traditional risk factors for cardiovascular disease." (PMID 36680616, 2023). "YTHDC2/circYTHDC/TET2 axis may become a potential therapeutic target for cardiovascular disease." (PMID 34660707, 2021). "Our data are in keeping with previous studies of CHIP in cardiovascular disease, and further studies into the therapeutic potential of NLRP3 inhibition for individuals with TET2 CHIP may be warranted." (PMID 38357791, 2024).
infection (32 papers, 2016 to 2026). The state of being infected such as from the introduction of a foreign agent such as serum, vaccine, antigenic substance or organism. "Host gene variants involved in trafficking (FYCO1 and RAB7A) and immune signaling (FOXA2, SFTPD, STAT3, and TET2) were associated with differential infection profiles." (PMID 41683583, 2026). "Infection of these differentiated cells with lenti-virus (IRES-GFP) coding for the KITD816V allele reiterates the TET2 and KIT mutations found in patient mast cell clones." (PMID 35393954, 2022). "Infection-induced inflammation, which can be corrected by antibiotics, shows positive correlation with myeloid expansion in TET2 deficient mice." (PMID 34512655, 2021). "As a result, mice deficient in Cxxc5, or to a lesser extent Tet2, were more vulnerable to infection by herpes simplex virus and vesicular stomatitis virus due to an impaired interferon response." (PMID 30809228, 2019). "Moreover, at the intersection of metabolic and transcriptional reprogramming, we identified infection-associated gene expression changes in chromatin-modulating enzymes, including Tet2, and their metabolite co-factors, such as α-KG." (PMID 42198775, 2026). "MDS patients with DM have an inferior prognosis which may due to higher infection incidence, with TET2 and SF3B1 mutations being more frequent in those cases." (PMID 38305890, 2024). "Overall, our results show that TET2 mutations in hHSPCs interfere with the ability of derived neutrophils to sense and respond to microbes and mount a balanced inflammatory response to sites of infection." (PMID 37267914, 2023). "Mechanisms implicated in DNA hypermethylation during H. pylori infection include inflammation associated with the infection and altered expression or activity of DNA methylation related enzymes; as an example, IL-1β is able to induce TET2 expression in macrophages via IL-1R-Myd88 signaling." (PMID 34394088, 2021). "Somatic TET2 mutations are among the most frequent reported mutations in human clonal hematopoiesis, which recently has been reported as an increased risk of certain infections caused by both virus and bacteria." (PMID 35011643, 2021). "Similarly, in a model of abdominal sepsis, Tet2 deficiency was shown to reduce infection-induced myelopoiesis with a decreased level of TNFα and chemokines." (PMID 30809228, 2019). "On one hand, extensive work with Tet2-KO mouse models have identified hematological stressors, such as aging, infection, and bone marrow transplant, that favor the expansion of TET2-CH, but supporting evidence in the human cell context remains scarce." (PMID 41342736, 2025). "By contrast, TET2 knockout HD11 cells exhibited a substantial decrease in global 5hmC levels at the same time point post-infection." (PMID 39840982, 2025). "Subsequent studies confirmed that ALV-J markedly reduced TET2 protein levels in these cells during the late stages of infection, utilizing the autophagy pathway." (PMID 39840982, 2025). "In CEF cells, TET2 expression initially increased significantly after infection, peaking at 24 h before decreasing at 36, 48, and 72 h." (PMID 39840982, 2025). "In this study, we observed the dynamics of TET2 protein expression in chicken cells post-infection with ALV-J, noting an initial increase followed by a decline." (PMID 39840982, 2025). "Taken together, these molecular data provide evidence that Tet2–/– neutrophils mediate a paradoxical state of enhanced inflammation but also reduced phagocytic capacity, which has clinical consequences during infection." (PMID 38573824, 2024). "Tet2 protein also significantly decreased in Nr2e3KO cells but increased in rescued cells after the infection with Nr2e3 lentivirus." (PMID 38881534, 2024). "But IAV endoribonuclease PA-X is able to remove the replication restriction by binding to TET2 mRNA and driving TET2 mRNA degradation to reduce TET2 expression during infection." (PMID 37498975, 2023).